CX3CL1 (C-X3-C motif chemokine ligand 1)
Diseases named in the same sentence as CX3CL1 in open-access papers (continued):
Sharing a sentence is not in itself a finding about the gene and the disease.
ovarian carcinoma (continued). "Furthermore, we wanted to know whether, in ovarian cancer cells, the transition of these forms is controlled by proteases, i.e. ADAM10 or ADAM17, which had been associated with CX3CL1 cleavage in other cell systems before." (PMID 39862711, 2025). "Thus, despite activating the adaptive immune system against ovarian cancer growth, most likely through T-cell recruitment, CX3CL1 overexpression promotes intraperitoneal tumour spread and shortens survival, very well reflecting the adverse prognostic impact in human HGSOC." (PMID 39862711, 2025). "Moreover, PARP inhibitors are able to increase CX3CL1 release from human ovarian cancer cells." (PMID 39862711, 2025). "Therefore, in this study, we used Sequenom Mass ARRAY technology to perform high-throughput analysis of CX3CL1 and CX3CR1 gene polymorphisms, aiming to explore the effect of CX3CL1 and CX3CR1 gene polymorphisms on the clinical efficacy of carboplatin in the treatment of ovarian cancer." (PMID 36685881, 2022). "Meanwhile, the CX3CL1/CX3CR1 coding region was found to have SNPs with various amino acid substitutions, such as the T280M SNP and V249I SNP, which would affect their expression, function and activity and may cause platinum resistance in ovarian cancer patients." (PMID 36685881, 2022). "Therefore, it is very important to explore whether the CX3CL1/CX3CR1 gene polymorphism is significantly related to the clinical treatment of ovarian cancer and to screen alleles related to clinical efficacy for the individualized treatment of ovarian cancer." (PMID 36685881, 2022). "Epithelial cells from malignant ascites, tumor specimens and from three ovarian cancer cell lines, namely BG1, OVCAR3 and SKOV3, displayed staining for CX3CL1." (PMID 21750716, 2011). "Previous work has mainly shown that the receptor for CX3CL1, CX3CR1, may promote proliferation, migration, and adhesion of ovarian cancer cells and thus promote tumour spread." (PMID 39862711, 2025). "In summary, specific features of the peritoneal milieu appear to be responsible for surpassing the adaptive anti-tumour immune response and for the negative net effect of CX3CL1 overexpression on tumour spread and survival in ovarian cancer." (PMID 39862711, 2025). "Here, we investigated the relationship between CX3CL1 and CX3CR1 genotypes and the clinical efficacy of carboplatin in ovarian cancer, thereby clarifying the unidentified genetic factors that influence the efficacy of carboplatin in ovarian cancer." (PMID 36685881, 2022). "One study found that CX3CL1 was expressed in ovarian epithelial cancer cells and detected in malignant ascites of patients as a novel malignant cell proliferation regulator." (PMID 36685881, 2022). "The overexpression of STK3 can promote ovarian cancer cells to secrete CXCL16 and CX3CL1." (PMID 33062724, 2020). "Furthermore, our studies indicated that the CX3CL1/CX3CR1 axis supported ovarian carcinoma cell adhesion and proliferation, further suggesting its potential pivotal role in development and progression of ovarian carcinoma metastasis." (PMID 24384839, 2013). "Our data suggest that, unlike in the ovarian carcinoma, autocrine activation of CX3CR1 by CX3CL1 in fallopian carcinoma cells may not occur." (PMID 26633537, 2015).
Cerebral ischemia (14 papers, 2012 to 2024). Restriction of arterial blood supply to the brain associated with insufficient oxygenation to support the metabolic requirements of the tissue. "In the CCH phase, prolonged low levels of CCL11 are detrimental to the prognosis of patients with cerebral ischemia; CX3CL1, XCL-1 and CCL2/MCP-1 exert neuroprotective effects." (PMID 39206161, 2024). "During cerebral ischemia, neurons release soluble CX3CL1, which reduces neuronal damage by binding to CX3CR1 in brain tissue and inhibiting microglia activation." (PMID 39206161, 2024). "In rodent models, the intracerebroventricular administration of exogenous CX3CL1 provides a long-lasting neuroprotective effect against cerebral ischemia." (PMID 35955921, 2022). "According to this statement, the intracerebroventricular administration of exogenous CX3CL1 results in a long-lasting neuroprotective effect against cerebral ischemia in rodents." (PMID 33065974, 2020). "We have previously demonstrated that exogenous CX3CL1 has a long-lasting neuroprotective action in vivo against pMCAO in rodents reducing neurological deficits and infarct size related with cerebral ischemia." (PMID 31607865, 2019). "The data reported in this paper suggest that CX3CL1 protects against cerebral ischemia modulating the activation state of microglia and its metabolism in order to restrain inflammation and organize a neuroprotective response against the ischemic insult." (PMID 31607865, 2019). "Controversially, genetically CX3CL1- and CX3CR1-deficient mice are also less susceptible to cerebral ischemia." (PMID 24722201, 2014). "To date, little is known about the CX3CL1/CX3CR1 pathway in the context of microglia activation following brain ischemia." (PMID 24490760, 2014). "In this view, we hypothesized that CX3CL1 is neuroprotective, in permanent focal cerebral ischemia, due to its ability to modulate microglia polarization and activation state toward a protective one." (PMID 31607865, 2019). "We previously demonstrated that CX3CL1 is protective against cerebral ischemia." (PMID 31607865, 2019). "Our previous study showed that CX3CL1 has neuroprotective effect against cerebral ischemia." (PMID 31607865, 2019). "We have previously shown that CX3CL1 has neuroprotective effects against cerebral ischemia injury." (PMID 31607865, 2019). "It has been shown that CX3CL1 is neuroprotective in cultured rat hippocampal neurons and Cx3cr1−/− mice show reduced damage after cerebral ischemia; this protection may be due to the anti-inflammatory state of local microglia." (PMID 28955220, 2017). "Paulina Pawelec found that injection of exogenous CX3CL1 into the ventricles stimulated endothelial cell proliferation and migration in the ischemic semidark zone, resulting in increased vascular density and a durable neuroprotective and pro angiogenic effect in rodents with cerebral ischemia." (PMID 39206161, 2024). "However, when they administering CX3CL1 to the CX3CL1 deficient mice they found aggravated the brain ischemia, possibly related to the constitutive lack of CX3CL1 leading to a maladaptation of the CX3CL1/CX3CR1 signaling axis." (PMID 30319362, 2018). "Furthermore, there are also data postulating that the disruption of CX3CL1/CX3CR1 communication by the deletion of the cx3cr1 gene causes neurotoxicity in mouse models of systemic inflammation PD and ALS but protects against neuronal loss in a mouse model of focal cerebral ischemia." (PMID 35955430, 2022). "The rat brain ischemia model shows that chemokines C–C motif chemokine ligand 2 (CCL25) and C-X3-C motif chemokine ligand 1 (CX3CL1) can also influence MSC chemotaxis." (PMID 35378955, 2022). "The work presented here provides important in vivo evidence for the role of the CX3CL1/CX3CR1 signaling pathway in the activation and neurotoxicity of microglia/ macrophage in cerebral ischemia." (PMID 24490760, 2014).
Cerebral ischemia (continued). "However, theinhibitory effects of neurons on the microglial inflammation are likelydisrupted if the CX3CL1 and/or CX3CLR expressions are altered under apathological state, such as cerebral ischemia." (PMID 37908770, 2023). "These datasupport the contention that neuronal autophagy aggravates the microglialinflammatory injury by down-regulating the CX3CL1 expression on neurons.However, the study failed to elucidate the direct regulative mechanism ofneuronal autophagy on a microglial inflammation after cerebral ischemia." (PMID 37908770, 2023). "Since it was demonstrated that during the progression of cerebral ischemia microglia phenotype changes from anti- to pro-inflammatory and microglia express CX3CR1, we investigated whether the neuroprotective effect of CX3CL1 in ischemia is due to its ability to change the phenotype of microglia." (PMID 31607865, 2019).
coronary artery disease (14 papers, 2011 to 2025). "A clear link between CX3CL1 levels, polymorphisms, and coronary artery disease in humans is well defined." (PMID 24995121, 2014). "CX3CL1 levels may be associated with coronary artery disease severity, since elevations were observed in patients with acute myocardial infarction and unstable angina pectoris compared to stable angina pectoris." (PMID 36555579, 2022). "The effects of altered CX3CL1 expression have been documented in other inflammatory diseases like coronary artery disease (CAD) and kidney disease." (PMID 38731913, 2024). "CX3CR1 and CX3CL1 contribute to CVD morbidity in persons without HIV infection: polymorphisms in CX3CR1 are associated with coronary artery disease; numbers of CX3CR1-expressing cells and plasma CX3CL1 levels predict plaque rupture in unstable angina." (PMID 32976527, 2020). "Among the results, it was seen that the plasma levels of CCL2 and CX3CL1 were elevated in patients with ACS compared with patients with stable coronary artery disease, and the TC levels in ACS patients of the chemokines CCL2, CCL5, and CX3CL1 were reduced by treatment with colchicine." (PMID 40859641, 2025). "Circulating CX3CL1 also correlated with plaque burden on intravascular ultrasound, as well as with plaque rupture in patients with unstable angina pectoris, providing confirmation of its potential role in the progression of coronary artery disease." (PMID 36555579, 2022). "Accordingly, CX3CR1 expression on CD8 T cells, endothelial production of CX3CL1, and T cell CX3CL1-mediated adhesion and chemotaxis are all increased in people with coronary artery disease, and attenuated following six months of statin therapy, which decreases risk of CVD events." (PMID 32976527, 2020). "CX3CL1 expression increases in the heart and serum of patients with end-stage heart failure due to coronary artery disease or dilated cardiomyopathy, which involves however different mechanisms from the compensated hypertrophy due to arterial hypertension or aortic stenosis." (PMID 27525724, 2016). "Thus, targeted inhibition of the ADAM10/CX3CL1 axis could interfere with the dynamic events triggering detrimental trained immunity and chronic inflammation in ischemic heart disease." (PMID 36496449, 2022). "On the other hand, concentrations and mRNA expression levels of CCL2, CCL5, and CX3CL1 have also been evaluated in patients with acute myocardial infarction and unstable angina, patients with stable angina, and patients without coronary heart disease." (PMID 40508161, 2025). "In this study we determined baseline CX3CL1 levels in human subjects without known coronary disease and after modulation of cholesterol levels using different statins to determine if CX3CL1 levels are linked to cholesterol levels or other inflammatory stimuli." (PMID 24995121, 2014). "The relationship between inflammatory cytokines, cholesterol, and CX3CL1 levels in human subjects without known coronary artery disease is not well characterized." (PMID 24995121, 2014). "Statin therapy significantly reduces the levels of CX3CL1 in the blood stream of human subjects without known coronary artery disease." (PMID 24995121, 2014). "However, the levels of CX3CL1 in asymptomatic subjects without known coronary disease have not been studied." (PMID 24995121, 2014). "To understand whether CX3CL1 levels vary with cholesterol levels or other factors in humans, we assessed CX3CL1 levels in human subjects without known coronary disease and used HMG-CoA reductase inhibitors (statins) of varying potencies to modulate cholesterol levels." (PMID 24995121, 2014). "In conclusion, we found that CX3CL1, GM-CSF, and VEGF-A levels are significantly decreased by statin therapy in adult human subjects without known coronary artery disease." (PMID 24995121, 2014).
glioblastoma (14 papers, 2012 to 2024). The most malignant astrocytic tumor (WHO grade IV). "CX3CL1 was below the lower limit of detection in supernatants from all dissociated glioblastoma tumour biopsy, CUSA and GNS cell samples analysed." (PMID 35464424, 2022). "Genes that show higher expression in astrocytoma compared to glioblastoma were CX3CL1, CSF1 (MCSF), CCL3 (MIP1α), CCL4 (MIP1β), TGFα, FLT3LG, CXCL5, CCL19 while KITLG (SCF) and NGF were equally expressed in the two tumor types." (PMID 35301393, 2022). "The chemokine CX3CL1 is involved in the recruitment of TAMs to the glioblastoma TME via tumor secretion and subsequent binding to CX3C receptor 1 (CX3CR1) on TAMs." (PMID 34503065, 2021). "While predominantly CX3CL1/CX3CR1 signalling is related to tumor progression, inactivation of the CX3CL1/CX3CR1 axis was shown to enhance glioblastoma development." (PMID 34988021, 2021). "We present the role of CX3CL1 in the development of active human cytomegalovirus (HCMV) infection in glioblastoma multiforme (GBM) brain tumors." (PMID 32466280, 2020). "Considering that only the soluble form would be present in supernatants, this may explain why CX3CL1 protein was below the limit of detection for all glioblastoma biopsies and GNS cell-lines analysed despite varying proportions of cells expressing CX3CL1 identified by scRNA-seq analysis." (PMID 35464424, 2022). "The chemokine genes MIF, CCL2, CXCL8, CX3CL1 and CXCL2 were all highly expressed by the six glioblastoma primary lines." (PMID 36430641, 2022). "Meningiomas express several factors, which are known to have chemotactic properties on microglia in glioblastoma multiforme (e.g., CCL2, CX3CL1, SDF-1, G-CSF and GM-CSF)." (PMID 34503077, 2021). "The tumor tissues of BRCA, lymphoid neoplasm diffuse large B-cell lymphoma (DLBC), glioblastoma multiforme (GBM), LUAD, pancreatic adenocarcinoma (PAAD), rectum adenocarcinoma (READ), stomach adenocarcinoma (STAD), and thymoma (THYM) contained significantly elevated levels of CX3CL1." (PMID 37153002, 2023). "We detected high level US28-specific release of Ca++ in response to CCL5/RANTES or CX3CL1/Fractalkine in primary smooth muscle cells but not in the glioblastoma derived cells, although it is currently unclear why US28 would fail to induce this response in the glioblastoma cells." (PMID 23209769, 2012). "Furthermore, both CCL5 and CX3CL1 promote US28-dependent Ca2+ mobilization in a PTX-insensitive manner in HCMV-infected smooth muscle cells, but not in U373 glioblastoma cells." (PMID 25805993, 2015).
lung fibrosis (14 papers, 2018 to 2025). "CX3CL1 on endothelial cells, along with increased soluble CX3CL1, associates with pulmonary fibrosis severity." (PMID 39768150, 2024). "An association between elevated serum CX3CL1 and disease severity, increased frequency of pulmonary fibrosis, and lower DLco in lungs was also reported." (PMID 33105647, 2020). "Analysis of the secondary endpoints demonstrated, that CX3CL1 in univariable analyses associates with new onset of significant lung fibrosis (progressed from <10% lung fibrosis to >10%)." (PMID 30457999, 2018). "In multivariable analyses, CX3CL1 (OR 1.4, 95% CI 1.06–1.84, p = 0.016) and the extent of baseline fibrosis (OR 1.5, 95% CI 1.26–1.74), p<0.001) were associated with new onset of significant lung fibrosis (AUC = 0.87)." (PMID 30457999, 2018). "In the respiratory tract, CX3CL1 has also been proposed to support the migration of monocytes in interstitial lung disease and to promote pulmonary fibrosis by attracting macrophages with a pro-fibrotic phenotype." (PMID 41081526, 2025). "We next evaluated the efficacy of CX3CL1 antagonism for lung fibrosis induced by cGVHD using lung samples 42 days after BMT." (PMID 38702742, 2024). "In mice, local Cx3cl1 in response to bleomycin promotes pulmonary fibrosis by attracting Cx3cr1-expressing M2 macrophages and fibrocytes." (PMID 39768150, 2024). "The current study demonstrated that neutralizing anti-CX3CL1 mAb inhibited the progression of both skin and lung fibrosis in the Scl-cGVHD mouse model." (PMID 38702742, 2024). "The concentration of CX3CL1 was significantly higher in patients suffering from idiopathic pulmonary fibrosis (IPF) and hypersensitivity pneumonitis patients compared to the control group." (PMID 34208027, 2021). "It has been shown that CX3CL1 recruits natural killer (NK) cells, which protects mice against bleomycin-induced lung fibrosis." (PMID 33688918, 2021). "Although the inhibition of CX3CL1 only negligibly affected lung fibrosis, marked changes were observed in CX3CR1+ cells that had abundantly infiltrated the alveolar space." (PMID 34067842, 2021). "CX3CL1 was associated with extent of fibrosis at baseline and progressive ILD including lung fibrosis and DLCO decline." (PMID 30457999, 2018). "In SKG mice, lung fibrosis becomes evident several weeks after an injection of zymosan A. A different treatment outcome may have been observed if anti-CX3CL1 mAb had been administered once lung fibrosis was established." (PMID 34067842, 2021). "CX3CL1 was associated with annual progression of pulmonary fibrosis > 5% in univariable analyses, no further analyses were performed due to low events (n = 9)." (PMID 30457999, 2018). "In the Oslo cohort, CX3CL1 correlated with anti-Topoisomerase-I-antibody and lung fibrosis." (PMID 30457999, 2018). "In line with our data, they found that circulating CX3CL1 was associated with the severity of pulmonary fibrosis evaluated on chest x-ray, and not with PH." (PMID 30457999, 2018). "Therefore, anti-CX3CL1 mAb treatment significantly inhibited the lung fibrosis of Scl-cGVHD mice." (PMID 38702742, 2024). "Secondly, CX3CL1 levels were examined in sera in a large and unselected cohort with longitudinal follow-up data including complete lung follow up data with function tests, lung fibrosis as assessed by HRCT, ECHO as well as RHC data resulting in reliable data on clinical associations to CX3CL1." (PMID 30457999, 2018). "Anti-CX3CL1 mAb therapy reduced the number of BALF M1 macrophages, but not M2 macrophages, in SKG-ILD, and only negligibly attenuated lung fibrosis in SKG-ILD." (PMID 34067842, 2021). "In idiopathic pulmonary fibrosis (IPF) and ILD in polymyositis or dermatomyositis (PM/DM), CX3CL1 is expressed on fibroblasts, inflammatory cells, and alveolar macrophages in addition to the epithelia and vessels." (PMID 34067842, 2021).